CHCHD2 (coiled-coil-helix-coiled-coil-helix domain containing 2)
Diseases named in the same sentence as CHCHD2 in open-access papers (continued):
Sharing a sentence is not in itself a finding about the gene and the disease.
Hepatic fibrosis (2 papers, 2022 to 2024). The presence of excessive fibrous connective tissue in the liver. "CHCHD2 knockout greatly suppressed TAA-induced liver fibrosis, as evidenced by Sirius red staining and reduced expression levels of Des, Timp1, transforming growth factor-β (Tgfb), Col1a1 (P = 0.055), and Col3a1 (P = 0.054)." (PMID 36477358, 2022). "To investigate the role of Notch signaling in CHCHD2 overexpression–induced liver fibrosis in NASH mice, we treated mice with the Notch inhibitor DAPT." (PMID 36477358, 2022). "We also found Notch inhibition attenuated CHCHD2 overexpression–induced liver fibrosis in vivo and in vitro." (PMID 36477358, 2022). "In contrast, CHCHD2 overexpression led to increased liver fibrosis in mice fed a normal or MCD/HFD diet." (PMID 36477358, 2022). "The inhibition of Notch signaling attenuates liver fibrosis exacerbated by CHCHD2 overexpression in NASH mice." (PMID 36477358, 2022). "Notably, hepatocyte-specific CHCHD2 overexpression further exacerbated liver fibrosis in NASH mice, as shown by Sirius red staining." (PMID 36477358, 2022). "Therefore, increased CHCHD2 levels in hepatocytes promoted liver fibrosis by Notch/OPN signaling in NASH livers." (PMID 36477358, 2022). "Moreover, Notch inhibition attenuated CHCHD2 overexpression–induced liver fibrosis in vivo and in vitro." (PMID 36477358, 2022). "CHCHD2 deletion attenuates liver fibrosis in NASH and thioacetamide-treated mice." (PMID 36477358, 2022). "This indicates that CHCHD2 is a potential target for liver fibrosis." (PMID 36477358, 2022). "Elevated hepatocyte CHCHD2 accelerates the evolution of hepatic fibrosis." (PMID 36477358, 2022). "Coiled-coil-helix-coiled-coil-helix domain-containing 2 (CHCHD2) is upregulated via YAP/TAZ-TEAD in NASH livers and consequently promotes liver fibrosis by activating the NOTCH pathway and enhancing OPN production." (PMID 38276550, 2024). "In conclusion, CHCHD2 is upregulated via YAP/TAZ-TEAD in NASH livers and consequently promotes liver fibrosis by activating the Notch pathway and enhancing osteopontin production." (PMID 36477358, 2022). "Taken together, these data indicate that CHCHD2 increases OPN expression via Notch activation and promotes liver fibrosis." (PMID 36477358, 2022). "Increased CHCHD2 promotes liver fibrosis in NASH mice, which may be mediated by activation of the Notch/OPN pathway in hepatocytes." (PMID 36477358, 2022). "In addition, TAA-induced liver fibrosis was greatly improved by absence of CHCHD2." (PMID 36477358, 2022).
Huntington disease (2 papers, 2024). Huntington disease (HD) is a rare neurodegenerative disorder of the central nervous system characterized by unwanted choreatic movements, behavioral and psychiatric disturbances and dementia. "Using brain organoids models, Prigione and colleagues uncovered the impact of Huntington’s disease on human brain developmental and identified early dysregulation of CHCHD2, which disrupted mitochondria and might serve as a therapeutic target." (PMID 39174523, 2024).
nonalcoholic fatty liver disease (2 papers, 2022 to 2023). "Specifically, hepatocyte CHCHD2 contributed to liver fibrosis in nonalcoholic fatty liver disease (NAFLD), whereas CHCHD3 was found to improve mitochondrial function via increasing mitochondrial ROS and promoting ferroptosis, by which modulated tumorigenesis." (PMID 37438854, 2023). "Herein, we systematically characterized the role of CHCHD2 as a transcription factor by chromatin immunoprecipitation sequencing and found its target genes were enriched in nonalcoholic fatty liver disease (NAFLD)." (PMID 36477358, 2022).
synucleinopathies (2 papers, 2021 to 2024). "Understanding the pathophysiological implications of CHCHD2 mutations in vivo will not only shed light on the mechanisms underlying PD and other synucleinopathies, but also provide therapeutic interventions for PD and other Lewy body disorders." (PMID 33967741, 2021). "Thus, we propose that cutaneous synucleinopathies are highly similar between PD patients with CHCHD2 T61I mutations and those with iPD." (PMID 38751879, 2024). "Patients carrying LRRK2, CHCHD2, and GBA mutations, as well as those with iPD, displayed similar co-neuropathologies, including positivity for p-α-syn, α-syn, ASyO5, 5G4 (synucleinopathy), and HT7 and AT8 (p-tauopathy)." (PMID 38751879, 2024). "Furthermore, skin biopsy synucleinopathy associated with the RAB39B E179fsX48 mutation was found solely in Asians, similar to that observed with CHCHD2, which needs further verification." (PMID 38751879, 2024). "Despite multiple connections between α-synuclein and mitochondrial pathogenesis, the mechanistic basis for the role of CHCHD2 and α-synucleinopathy still remains unclear, albeit with a few tantalizing observations." (PMID 33967741, 2021). "In this study, identical mutation sites in CHCHD2 (T61I), LRRK2 (G2019S, R1441G), SNCA (E46K, A53T, duplication), and GBA (N370S, E326K, L444P, N409S/D409H) were identified in both skin biopsies and brain autopsies, with synucleinopathy detected in both cutaneous and cerebral samples." (PMID 38751879, 2024). "In conclusion, our study of peripheral cutaneous synucleinopathy characteristics in patients with genetic PD yielded several key findings: (i) P-α-syn was deposited in the peripheral cutaneous nerves of PD patients with CHCHD2, LRRK2, or GBA mutations but not in those with RAB39B or PRKN mutations." (PMID 38751879, 2024).
autosomal dominant Parkinson disease 22 (1 paper, 2019). "Heterozygous mutation in the CHCHD2 gene may be a rare cause of autosomal dominant Parkinson disease 22 (PARK22, OMIM#616710)." (PMID 30678103, 2019).
dementia with (1 paper, 2017). "Although little is known about the physiological roles of Coiled-Coil-Helix-Coiled-Coil-Helix Domain Containing 2 (CHCHD2) or its role in PD pathology, several mutations in the CHCHD2 gene cause an autosomal dominant form of late-onset PD and dementia with Lewy bodies." (PMID 29204154, 2017).
endometriosis (1 paper, 2024). The growth of functional endometrial tissue in anatomic sites outside the uterine body. "For example, in endometriotic tissues, CHCHD2 (Coiled-Coil-Helix-Coiled-Coil-Helix Domain Containing 2) expression may contribute to the pathogenesis of endometriosis through its regulation of mitochondria-mediated apoptosis." (PMID 38397379, 2024).
essential tremor (1 paper, 2025). A relatively common disorder characterized by a fairly specific pattern of tremors which are most prominent in the upper extremities and neck, inducing titubations of the head. "Similarly, in one of the original Japanese families with CHCHD2 p.(Thr61Ile), one variant carrier had a diagnosis of essential tremor and not of PD." (PMID 41465155, 2025).
fibrosis (1 paper, 2022). the formation of excess fibrous connective tissue in an organ or tissue in a reparative or reactive process. "Moreover, CHCHD2 expression was associated with the stage of fibrosis in these patients; patients with S3–4 fibrosis showed higher CHCHD2 expression than the other groups." (PMID 36477358, 2022). "In this study, we found that the expression level of CHCHD2 was greatly increased in patients with NAFLD and was positively associated with fibrosis." (PMID 36477358, 2022). "Expression of CHCHD2 is increased in patients with NAFLD and is positively related to fibrosis." (PMID 36477358, 2022).
head and neck cancer (1 paper, 2025). A primary or metastatic malignant neoplasm affecting the head and neck. "Consequently, we further investigated the role of CHCHD2 in head and neck cancers as well as NPC." (PMID 40434251, 2025).
liver diseases (1 paper, 2022). "We thank Jun Cheng from Beijing Ditan Hospital for suggestions on exploring CHCHD2 function in liver diseases." (PMID 36477358, 2022).
melanoma (1 paper, 2021). A malignant, usually aggressive tumor composed of atypical, neoplastic melanocytes. "Interestingly, frequent mutations in the hotspot in the 5’UTR of CHCHD2 were previously reported in melanoma." (PMID 34900699, 2021). "We also found that the identified BAD and CHCHD2 mutations frequently occur in melanoma but not in other cancers via The Cancer Genome Atlas analysis." (PMID 34900699, 2021).
mitochondrial encephalomyopathy (1 paper, 2023). A heterogenous group of disorders characterized by alterations of mitochondrial metabolism that result in muscle and nervous system dysfunction. "In DW7 cells with mtDNA mutations linked to mitochondrial encephalomyopathy, CHCHD2 is decreased, whereas the enforced expression of CHCHD2 results in increases in the mitochondrial volume, mtDNA content, mitochondrial respiration, cellular levels of ATP, and ROS scavenging." (PMID 37109535, 2023). "Additionally, a reduction in CHCHD2 levels has been observed in mitochondrial encephalomyopathy-related mutant cells, leading to impairments in the UPRmt and mitophagy." (PMID 37109535, 2023).
mitochondrial myopathies (1 paper, 2021). "Previous studies have evaluated the prevalence of CHCHD2 and CHCHD10 mutations in Italian mitochondrial myopathy patients without mitochondrial DNA mutations." (PMID 33967741, 2021).
skin cancer (1 paper, 2021). "Highest frequencies of individual somatic variants in the TLSs of NBPF20 and CHCHD2 reached 10.1% among LAML and 8.1% among skin cancer patients, respectively." (PMID 34072580, 2021).
steatosis (1 paper, 2022). Increased lipid within the cytoplasm of cells. "Moreover, Oil Red O staining and immunohistochemical staining of F4/80 showed that CHCHD2 knockout did not affect steatosis and macrophage infiltration in the livers of mice with NASH." (PMID 36477358, 2022).
teratoma (1 paper, 2024). A non-seminomatous germ cell tumor characterized by the presence of various tissues which correspond to the different germinal layers (endoderm, mesoderm, and ectoderm). "However, KO hESCs-derived teratoma also developed a neural rosette structure similar to WT hESCs, and no distinct alteration was observed in the three germ layers, which was consistent with the normal development of CHCHD2 KO mice." (PMID 38214772, 2024).
Zika virus infection (1 paper, 2019). "Our previous study found that CHCHD2 can be induced by Zika virus infection in HeLa cells and may promote ZIKV replication and inhibit virus-induced IFN-I production." (PMID 31757042, 2019).
neurodegenerative disease (20 papers, 2017 to 2026). A disorder of the central nervous system characterized by gradual and progressive loss of neural tissue and neurologic function. "Few studies have examined the role of CHCHD2 mutations in the pathogenesis of other neurodegenerative diseases." (PMID 40963812, 2025). "We further uncovered previously unrecognized associations between mutant CHCHD2 and neurodegenerative disease-related genes." (PMID 41237231, 2025). "Since the discovery in 2015 that CHCHD2 mutations are associated with neurodegenerative diseases, researchers have sought to validate the pathogenic mechanisms mediated by these mutations through the establishment of cellular and animal models." (PMID 40963812, 2025). "While the types of CHCHD2 mutations vary across different diseases and populations, a significant association between this gene and neurodegenerative disease pathogenesis appears likely." (PMID 40963812, 2025). "CHCHD2, a mitochondrial regulatory factor, plays a crucial role in mitochondrial homeostasis and function and is strongly linked to neurodegenerative diseases." (PMID 40963812, 2025). "Since neurons are highly sensitive to mitochondrial health, abnormalities or deficiencies in CHCHD2 can easily lead to neuronal damage and cell death, thereby contributing to the onset and progression of neurodegenerative diseases." (PMID 40963812, 2025). "In summary, the role of CHCHD2 mutations in the pathogenesis of neurodegenerative diseases remains a topic of debate, influenced by racial, geographic, and familial factors." (PMID 40963812, 2025). "Other notable variants of the CHCHD2 gene have been found in further studies of neurodegenerative diseases in Japan and China." (PMID 33967741, 2021). "In this review, we will focus on two of these proteins that have very recently been associated with neurodegenerative diseases, MNRR1/CHCHD2 and CHCHD10." (PMID 28685009, 2017). "CHCHD10 and CHCHD2 are mitochondrial proteins that reside in the intermembrane space and regulate electron flow through the electron transport chain during oxidative phosphorylation, and have been linked to multiple neurodegenerative diseases." (PMID 41496579, 2026). "Although the precise molecular mechanism remains unclear, this finding opens new avenues for future research into the treatment of CHCHD2-associated neurodegenerative diseases." (PMID 40963812, 2025). "Mutations in CHCHD2 may influence the mechanisms of neurodegenerative diseases through both loss-of-function and gain-of-function effects, with overexpression possibly reversing pathological processes and mitochondrial dysfunction." (PMID 40963812, 2025). "Collectively, these studies suggest that toxic gain-of-function mechanisms may play a key role in CHCHD2 mutation-induced neurodegenerative diseases." (PMID 40963812, 2025). "Additionally, CHCHD2 is being explored as a potential therapeutic target for neurodegenerative diseases, particularly in terms of loss-of-function and gain-of-function mechanisms." (PMID 40963812, 2025). "Disease-associated mutations of CHCHD2 in neurodegenerative diseases." (PMID 33967741, 2021). "This review summarizes and discusses the structure and function of CHCHD2, its links to neurodegenerative diseases, and current targeted mitochondrial therapeutic strategies." (PMID 40963812, 2025). "Further studies are essential to examine the genetic landscape of affected populations, which will help validate the relationship between CHCHD2 and neurodegenerative diseases and support its consideration as a potential therapeutic target." (PMID 40963812, 2025). "CHCHD2 and CHCHD10 are homologous mitochondrial proteins and their mutations are identified with neurodegenerative disease." (PMID 35173147, 2022). "In recent years, mutations at two mitochondrial homologous proteins CHCHD2 and CHCHD10 have been identified as a wild spectrum of neurodegeneration disease." (PMID 35173147, 2022).
neurodegenerative disease (continued). "Secondly, a number of studies based on iPSC models of neurodegenerative disease have reported CHCHD2 mis-regulation and suggested this as a factor contributing to disease pathology." (PMID 34660586, 2021). "While CHCHD2 and CHCHD10 share significant similarities in sequence, secondary structure, expression pattern, and function, mutations in CHCHD2 and CHCHD10 are associated with distinctly different neurodegenerative diseases." (PMID 33967741, 2021). "Further, we discuss the necessity of continued investigation into the divergent functions of CHCHD2 and CHCHD10 to determine how mutations in these similar mitochondrial proteins contribute to different neurodegenerative diseases." (PMID 33967741, 2021). "Subsequent studies have demonstrated that CHCHD2 and CHCHD10 are associated with a variety of dominantly inherited neurodegenerative diseases as well as sporadic neurodegenerative diseases." (PMID 30791515, 2019). "Although CHCHD2- and CHCHD10-linked neurodegenerative diseases are dominantly inherited, the findings of their mutations leading to premature protein truncation suggest mitochondrial phenotypes arise from haploinsufficiency." (PMID 30791515, 2019). "The top-ranking transcripts ranked by Manhattan distance included CHCHD2 (also known as MNRR1) and Clusterin (CLU) upregulation, with downregulation of FABP3 and S100A4, modulation, all having previously been associated with neurodegenerative disease;." (PMID 41173878, 2025). "These insights could inform the identification of therapeutic targets in neurodegenerative diseases and shape future research on CHCHD2." (PMID 40963812, 2025). "Our results suggest that positive modulation of CHCHD2-mediated protective mechanism against oxidative damage in neuronal cells may provide novel neuroprotective strategies for treatment of HD and other neurodegenerative diseases." (PMID 38341417, 2024). "We test whether the degradation rate of neurodegenerative disease-related CHCHD2 mutants would behave similarly to CHCHD2 in wildtype." (PMID 35173147, 2022). "Western Blot analysis showed that the degradation rate of CHCH2 mutants, T61I and R145Q, was significantly slower than that of the wild-type CHCHD2, indicating that neurodegenerative disease-related CHCHD2 mutants are resistant to degradation by Yme1L and OMA1 under mitochondrial stress." (PMID 35173147, 2022). "Despite the presence of rare pathogenic CHCHD2 mutations in early-onset PD and other neurodegenerative diseases, other studies have failed to provide evidence for genetic association of CHCHD2 to PD." (PMID 33967741, 2021). "In addition, distinct patterns in T61I homozygous compared to T61I heterozygous and KO mice (cluster 2) highlighted Dnajc11, a cristae-structural protein not previously implicated in CHCHD2 biology, as a potential contributor to neurodegenerative disease." (PMID 41237231, 2025). "Although research suggests that CHCHD2 is involved in the mechanisms underlying various neurodegenerative diseases, there is a notable absence of comprehensive studies that integrate different mutation types, pathogenic mechanisms, and targeted treatment strategies." (PMID 40963812, 2025). "Consequently, many researchers have begun to explore treatments for neurodegenerative diseases from the perspective of mitochondrial defects, with or without CHCHD2 mutations, in an effort to discover new therapeutic strategies." (PMID 40963812, 2025). "This review synthesizes evidence related to the functions of CHCHD2 and CHCHD10 and their molecular mechanisms in the progression of neurodegenerative diseases, providing implications for novel strategies in brain injury." (PMID 36061599, 2022). "In this review, we summarize the present knowledge about the physiological and pathological roles of twin proteins, CHCHD2 and CHCHD10, in neurodegenerative diseases." (PMID 30791515, 2019).
neurodegenerative disease (continued). "Although multiple studies suggest an association between CHCHD2 and neurodegenerative diseases in the Chinese population, some research indicates that CHCHD2 may not play a key role in the pathogenesis of neurodegenerative diseases." (PMID 40963812, 2025).